WNT2 (Wnt family member 2)
Diseases named in the same sentence as WNT2 in open-access papers (continued):
Sharing a sentence is not in itself a finding about the gene and the disease.
cancer (89 papers, 2006 to 2025). A tumor composed of atypical neoplastic, often pleomorphic cells that invade other tissues. "Cancer-associated fibroblasts (CAFs) secrete WNT2, which blocks DC differentiation, and maintain immunosuppressive stroma through YAP1 activation." (PMID 41050070, 2025). "Cancer-associated fibroblasts secrete WNT2 to suppress the functions of DCs in TME, and targeting WNT2 restores DC differentiation and enhances the efficacy of immune checkpoints inhibitors." (PMID 37936694, 2023). "The genetic findings, supported by the functional experiments, suggest a new cancer syndrome caused by aberrant activation of WNT2 that predisposes to SI-NETs and intestinal adenocarcinomas." (PMID 34274970, 2021). "We experimentally demonstrated decreased EZH2 binding to the hypermethylated promoter region of WNT2 in cancer cells relative to normal cells, in association with higher expression of WNT2 in cancer." (PMID 32699215, 2020). "The secretion of WNT2 from cancer-associated fibroblasts is an important factor that promotes ESCC motility and invasiveness." (PMID 32766155, 2020). "Cancer-associated fibroblast-secreted WNT2 acts as a growth- and invasion-promoting factor in ESCC cells." (PMID 32766155, 2020). "In human colon cancer, Wnt2 is selectively elevated in cancer-associated fibroblasts (CAFs), resulting in increased invasion and metastasis." (PMID 32983993, 2020). "Here, analysis of the gene expression profiles of primary cancer‐associated and normal fibroblasts isolated from surgical specimens revealed that Wnt2 plays a critical role in colorectal CAFs." (PMID 31468733, 2019). "According to reports, Wnt2 takes part in regulation of proliferation, differentiation and apoptosis of cells and has previously been linked to the progression of cancer." (PMID 30619457, 2018). "Wnt2 is implicated in various human cancers and upregulated in human cancer and contributed to tumorigenesis." (PMID 28665975, 2017). "As one of the Wnt family members, Wnt2 is closely associated with the development of several malignant tumors." (PMID 28665975, 2017). "Wnt pathway, which is known to regulate transcription activity and cause aberrant cell division and migration associated with cancer formation, was found indeed deregulated as documented by the downregulation of Wnt2, Nfatc1, and Nfatc4 genes." (PMID 26559525, 2015). "In cancer cells, Wnt2 expression is associated with anchorage-independent cell survival, metastasis, and tumor invasion." (PMID 26484565, 2015). "The expression of WNT2 in CAFs is associated with the invasion of cancer cells." (PMID 40677714, 2025). "Also, it was suggested that expression of Wnt2 in cancer cells is associated with the metastasis and tumor invasion." (PMID 33224221, 2020). "The analysis here involved comparing gene expression between cancer associated and normal fibroblasts using RNA sequencing, which identified that components of the Wnt signaling pathway were highly expressed in cancer associated fibroblasts, and Wnt2 in particular." (PMID 31468733, 2019). "While targeting WNT2 is a promising therapeutic strategy, challenges remain across different cancer models." (PMID 40453074, 2025). "WNT2 supports cancer stemness, chemoresistance, and angiogenesis, and is co-activated in TGFβ-rich microenvironments in reports." (PMID 41348904, 2025). "Both WNT2 and WNT7B showed elevated expression levels across individual cancer stages; in particular, WNT2 had higher expression at stage 1, whereas WNT7B had higher expression at stage 4 compared to normal tissues." (PMID 41044153, 2025). "In vitro studies have shown that Wnt2 promotes cancer cell migration and invasion, reinforcing its role in disease progression." (PMID 40943055, 2025). "WNT ligands (e.g., WNT2, WNT5A) from tumor cells and cancer-associated fibroblasts (CAFs) in the TME activate the Wnt pathway through the proliferation of CSCs and resurrection of dormant CSCs, causing treatment resistance and cancer recurrence." (PMID 38952556, 2024).
cancer (continued). "Wnt signalling activation has been observed in various cancer types, including colorectal cancer, where activators such as Wnt2, Wnt4, TGM2, and the long noncoding RNA GAS5 play a role." (PMID 38136392, 2023). "An increasing number of studies has shown that the expression of Wnt2 is abnormally high in various cancers, including fibroadenoma, breast cancer, and gastric cancer." (PMID 37374338, 2023). "It has been reported that circRNAs can promote the development of cancer through glutamine metabolism, and the WNT2/β-Catenin signaling pathway is related to glutamine metabolism in cancer." (PMID 33397440, 2021). "Meanwhile, we confirmed the existence of 3 genes (COX-2, IGF-1 and WNT2) which are known to be subjected to miR-30a-3p regulation in human cancer cells based on previous studies 9, 19-21." (PMID 34093801, 2021). "Studies have shown that a large amount of Wnt2 secretion can activate the wnt2-expanded catenin-protein signaling pathway and ultimately promote the growth of cancer cells." (PMID 34375306, 2021). "For KLF6→WNT2, the regulatory intensity was increased from normal (−0.383) to cancer (0.274), and accordingly, the expression level of the target, WNT2, was elevated." (PMID 32717065, 2020). "The authors observed Wnt2-induced cancer cell migration and invasion in CRC and confirmed the correlation between Wnt2 expression and clinicopathological data (including venous invasion) in CRC in vivo studies." (PMID 33276489, 2020). "We also found that the EZH2-binding site within the WNT2 promoter overlaps with the hyper-CpG methylation sites in the WNT2 promoter region in cancer cells." (PMID 32699215, 2020). "This suggests an acquisition of ERG binding and (de)regulation of WNT2 expression in the cancer cells which acquire the TMPRSS2-ERG fusion." (PMID 31818883, 2020). "Wnt2 affects the invasion and migration of cancer cells, proliferation, apoptosis, angiogenesis, and other adverse consequences." (PMID 32983993, 2020). "DNA methyltransferase inhibitor (5-Azacytidine) treatment partially decreased the methylation level in the promoter region of WNT2 and increased EZH2 binding, leading to the attenuation of WNT2 expression in cancer cells." (PMID 32699215, 2020). "Despite its role during lung and cardiac development, as well as in cancer progression, WNT2 is an important factor in placenta vascularization." (PMID 31667643, 2020). "Klein et al64 demonstrated that STC1 is a target gene of Wnt signalling and can be down‐regulated by Wnt2, which acts as an angiogenic growth factor and differentiation factor in vascular development during cancer progression." (PMID 32468698, 2020). "Previous studies have shown that Wnt2 is highly expressed in cancer cells compared with its expression in normal cells and that Wnt2 affects the invasion and migration of cancer cells, proliferation, apoptosis, angiogenesis, and other adverse consequences." (PMID 32983993, 2020). "Our study clearly revealed that CAFs release Wnt2 protein to cancer cells to promote CRC progression in a paracrine fashion." (PMID 31468733, 2019). "Positive staining for Wnt2 was mainly observed in cancer stroma, although the immunoreactivity was weak in cancer cells." (PMID 31468733, 2019). "In conclusion, Wnt2 secreted by CAFs plays a key role in cancer progression and is a potential therapeutic target for CRC." (PMID 31468733, 2019). "We also demonstrated that Wnt2 protein derived from CAFs induced cancer cell migration and invasion in CRC." (PMID 31468733, 2019). "As a result, cancer cell invasion and migration were significantly decreased in the CM from immortalized CAFs transfected with siRNA targeting Wnt2." (PMID 31468733, 2019). "Conversely, we focused on Wnt2 protein in culture media of CAFs enhancing the migration and invasion of cancer cells in CRC." (PMID 31468733, 2019).
cancer (continued). "Two WNT2-specific small interfering RNAs (siRNAs) were used to explore the effects of WNT2 on invasive and metastatic ability of cancer cells, and to reveal the possible mechanism of WNT2 affecting epithelial—mesenchymal transition (EMT)." (PMID 27513465, 2016). "Recent reports have uncovered the role of WNT2 in the development and progression of various cancers." (PMID 27513465, 2016). "On the other hand, resveratrol possesses multifaceted targeting capacities and the cancer-associated signaling pathways mediated by STAT3, Wnt2 and/or Notch1/2 have been known as its molecular targets." (PMID 25896424, 2015). "Wnt signaling is dysregulated in various tumors and Wnt-2 has been suggested to play an oncogenic role in cancer." (PMID 23815780, 2013). "The results demonstrate for the first time that there is an interaction between Wnt-2 and Frizzled-8 in cancer cells." (PMID 23815780, 2013). "In adult human breast tissue, WNT2 expression is restricted to stromal cells, whereas in cancers, elevated WNT2 expression has been detected also in epithelial cells, suggestive of an autocrine signaling loop." (PMID 21542898, 2011). "Nevertheless, ongoing preclinical and clinical studies suggest that targeting WNT2 could become a key tool in precision cancer therapy." (PMID 40453074, 2025). "Furthermore, findings from the CTRP database revealed that WNT2 was negatively correlated with all the anti-cancer drugs." (PMID 41044153, 2025). "Indeed, WNT2 up-regulation and loss of PI16 expression already have been reported in CAFs from advanced cancers." (PMID 37085135, 2023). "Additionally, oncogenic gene WNT2 was expressed several times lower in CD271+ cells compared to CD271− AD-MSCs: inhibitors of WNT2 are considered prime anti-cancer treatments." (PMID 33653407, 2021). "WNT2 protein was highly expressed in the cytoplasm of cancer cells relative to normal cells." (PMID 32699215, 2020). "Depletion of WNT2 could inhibit CRC, while cancer-associated fibroblasts (CAFs)-derived WNT2 could promote the progression of CRC." (PMID 32211321, 2020). "So, this study has raised the possibility that TINCR could modulate the role of the Wnt signaling pathway activated by Wnt2, through sponging miR-761, thereby controlling cancer progression." (PMID 32185226, 2020). "Accordingly, WNT2 protein expression was higher in three cancer cell lines." (PMID 32699215, 2020). "Previous studies showed that Wnt2 is upregulated in some cancers and leads to cancer progression." (PMID 31468733, 2019). "Furthermore, we examined the effects of Wnt2 expression on clinicopathological factors in patients with CRC and conducted in vitro analyses, which revealed that Wnt2 enhances cancer cell invasion and migration." (PMID 31468733, 2019). "Wnt2 is overexpressed and can promote tumorigenesis in many types of cancer." (PMID 28665975, 2017). "Intriguingly, Wnt2 upregulation was observed in various human cancers." (PMID 26484565, 2015). "Our results suggest that therapeutic strategies targeting Wnt-2 signaling may prevent the development of metastasis and have potential impact on cancer mortality." (PMID 23815780, 2013). "Since the dnhWnt-2 construct inhibited Wnt-2 signaling mediated by the Frizzled-8 receptor, we further investigated whether the dnhWnt-2 construct could inhibit cancer cell growth." (PMID 23815780, 2013). "However, immunoreactivity for Wnt2 was native or weak in cancer cells." (PMID 31468733, 2019). "However, it remains unknown how Wnt2 is upregulated in human cancer and contributes to tumorigenesis." (PMID 26484565, 2015). "In CRC, WNT2 promotes migration and invasion, while in gastric, pancreatic and NSCLC, it accelerates cancer progression." (PMID 40453074, 2025). "Epigenetic dysregulation of wnt/β-catenin signalling genes has been well characterized in cancers, examples ranging from promoter hypermethylation of WNT10B to histone modification-driven overexpression of WNT2." (PMID 41266313, 2025).
cancer (continued). "Future research should prioritize early-phase clinical trials to assess safety, dosing, and efficacy of anti-WNT2 monoclonal antibodies in OSCC and other cancers." (PMID 40453074, 2025). "Maximum of the cancers displayed the pattern, with enhanced expression of IL19, TGFβ-1, CXCR4, BMP1, VCAN, and WNT2 protein levels in the samples of KICH, KIRC, LUAD, LUSC especially BRCA when compared to normal samples." (PMID 41348904, 2025). "To investigate the patterns of WNT2, WNT7B, and WNT11 expression in various cancer types, we used TIMER2.0, to explore the expression levels of WNT2, WNT7B, and WNT11 in 33 cancer types and matched normal pairs from the TCGA and GTEx databases." (PMID 41044153, 2025). "Investigation of the genetic alteration status of WNT2, WNT7B, and WNT11 in patients with BRCA across various cancer cohorts using cBioPortal has revealed notable insights." (PMID 41044153, 2025). "Compared with normal stroma, Wnt2 is significantly overexpressed in CRC and promotes cancer cell invasion and metastasis by activating the Wnt signaling pathway." (PMID 37374338, 2023). "CCND1 is a downstream effector in the Wnt2/β-catenin pathway and activates the cyclin-dependent kinases (CDKs) CDK4 and CDK6 to promote cancer proliferation." (PMID 37056769, 2023). "WNT2, MSH6, RAF, and Cyclin D1 (CCND1), genes involved in cancer processes, were also differentially expressed after exposure to 10 μM and 30 μM DON." (PMID 34440667, 2021). "A panel of four pan-cancer markers (EGFR, EPCAM, HER2, and MUC1) and three putative PC markers (GPC1, WNT2, and GRP94) were investigated individually and together in plasma-derived exosomes." (PMID 33297544, 2020). "Wnt1 and Wnt2 were overexpressed in NSCLC samples and cancer cells, with Wnt1 expression exhibiting resistance to apoptosis-inducing therapy." (PMID 24260047, 2013). "We observed Wnt2 (wingless-related MMTV integration site 2) to be −13.8-fold repressed in cancer and -16.2-fold down regulated when compared to non-transgenic cells." (PMID 19812696, 2009). "In a recent study, Kalhor and colleagues assessed the three-dimensional structure of human Wnt2-Fzd7 CRD complex via bioinformatics approaches, and the data demonstrated a unique dynamic behavior of Wnt2 upon binding to Fzd7, which is highly useful in targeted therapy for Wnt2-related cancers." (PMID 32923386, 2020).
infection (5 papers, 2014 to 2019). The state of being infected such as from the introduction of a foreign agent such as serum, vaccine, antigenic substance or organism. "Human cytomegalovirus (HCMV) infection of human foreskin fibroblasts was associated with WNT5A and WNT5B downregulation, whereas HCMV infection elevated WNT2 expression in human mesenchymal stem cells." (PMID 31781093, 2019). "Wnt2 pathway has been suggested to contribute to the protection to pathogen infection and inflammation." (PMID 26098644, 2015). "From these studies it is known that infection of colon epithelial cells (CEC) with Salmonella typhimurium causes an increase in GSK3β-dependent β-catenin phosphorylation, leading to an upregulation of IL-6, IL-8, and Wnt2, via TLR5/NF-κB activation." (PMID 25136145, 2014). "The infected mice exhibited increased mRNA levels of canonical (Wnt1, Wnt2, Wnt3, and Wnt3a) and noncanonical (Wnt5a) Wnt molecules, receptors (Fz1 and Fz5) and the Wnt signalling target gene Sox9 in hepatocytes at 6 and 12 weeks post-infection." (PMID 28331224, 2017). "Knock-down of WNT2 and WNT3 (but not WNT1, CTNNB1, or LEF1) impaired infection of HeLa cells by Dengue virus." (PMID 31781093, 2019).
WNT2 also shares sentences with these, for which no sentence is quoted: neurodevelopmental disorder (3 papers); Fibroadenoma (2); Huntington disease (2); intrauterine growth restriction (2); oesophageal cancer (2); Parkinson disease (2); virus infection (2); acute myocardial infarction (1); adenocarcinoma (1); alcohol (1); Apert syndrome (1); autism spectrum disorder (1); bacterial infection (1); benign tumors (1); bladder cancer (1); cecum adenocarcinoma (1); cervical adenocarcinoma (1); cholestasis (1); Cognitive impairment (1); colitis (1); colon mucinous adenocarcinoma (1); colorectal polyps (1); connective tissue disorder (1); diabetic cardiomyopathy (1); gastrointestinal tract cancer (1); genitourinary cancer (1); gynecologic cancer (1); infectious disease (1); intestinal cancer (1); intestinal tumors (1).
A further 30 diseases each share a sentence with WNT2 in 1 paper.